APOE (apolipoprotein E)
Diseases named in the same sentence as APOE in open-access papers (continued):
Sharing a sentence is not in itself a finding about the gene and the disease.
coronary artery disease (264 papers, 2004 to 2026). "Variants in apolipoprotein E (ApoE) genotype, coupled with gene-environment interactions, substantially influence individual susceptibility to coronary artery disease." (PMID 40871049, 2025). "Numerous studies have investigated the role of ApoE polymorphisms in coronary artery disease (CAD); in particular, ApoE-ε4 allele has been extensively studied for its role in CV and cerebrovascular (CBV) diseases." (PMID 41465167, 2025). "The missense lead variant rs429358 at APOE, contributing to the APOE-E4 haplotype, is a risk locus for dyslipidaemia, Alzheimer's and coronary artery disease (CAD)." (PMID 39798939, 2025). "This lipid profile gradient is mirrored in cardiovascular risk, with coronary artery disease and myocardial infarction risk being the lowest among APOE ε2 carriers, intermediate in ε3 carriers, and the highest among ε4 carriers." (PMID 40943807, 2025). "According to a recent meta-analysis, those with the APOE ε4 allele have a 42% higher risk of developing coronary heart disease (CHD) than people with the common APOE ε3 allele." (PMID 39763652, 2024). "In a prospective general population cohort study involving approximately 91,000 subjects, APOE levels were linked to a higher risk of ischemic heart disease." (PMID 39571156, 2024). "APOE polymorphism is associated with an increased risk of coronary artery disease in Finnish adults." (PMID 39261765, 2024). "Specific genetic loci, such as the rs429358 polymorphism in apolipoprotein E, have been suggested to be closely associated with the development of coronary heart disease in Xinjiang Uyghurs." (PMID 36737734, 2023). "The meta-analysis aimed to evaluate the effects of apolipoprotein E gene variants on coronary artery diseases across various ethnic groups." (PMID 38021526, 2023). "The APOE locus is a common influence on the genetic structure of coronary artery disease and AD, and the association between the two vanishes when the impact of the APOE gene is excluded." (PMID 37665672, 2023). "Studies of white individuals have revealed a positive link between elevated levels of plasma apoE and cardiovascular-associated mortality as well as the risk of ischemic heart disease in males." (PMID 37400888, 2023). "A recent study showed that ApoE promotes metabolic processes involved in reverse cholesterol transport, which is associated with a lower risk of coronary heart disease." (PMID 37242746, 2023). "The most frequent author keywords included coronary heart disease, inflammation, apolipoprotein E (ApoE)-deficient mice, intima media thickness, endothelial dysfunction, oxLDL, and MI." (PMID 36082127, 2022). "APOE genetic variants also affect apolipoprotein B (apoB), whose relevance to ischemic heart disease (IHD) is increasingly acknowledged." (PMID 34203181, 2021). "Song Y, Stampfer MJ, Liu S. Meta-analysis: apolipoprotein E genotypes and risk for coronary heart disease." (PMID 32876203, 2020). "In particular, two different meta-analysis showed a different distribution of coronary disease risk according to ApoE genotype." (PMID 32485802, 2020). "Higher apoE levels in plasma HDL were previously found to be associated with lower coronary heart disease risk, but the coexistence of another apolipoprotein, apoC3, modified this lower risk." (PMID 32648923, 2020). "Wang CH, Zhou X. [Meta-analysis for relationship between apoE gene polymorphism and coronary heart disease]." (PMID 32876203, 2020). "The association between APOE genotype and coronary disease was described as a puzzling paradox in 2006; the paradox is still not solved." (PMID 32646381, 2020). "Genetically human apolipoprotein E (APOE) ε32 is associated with a decreased risk of ischemic heart disease." (PMID 31249639, 2019). "The proposed method also finds genes like APOE, which is strongly associated with familial early-onset AD and coronary heart disease, through analyses of AD-related genes and the gene–phenotype relationship." (PMID 31801521, 2019).
coronary artery disease (continued). "Regarding the ApoE, it has been observed that the ε4 allele of the ApoE4 is a major risk factor for coronary heart disease." (PMID 29614023, 2018). "Our previous study has reported that lower plasma PON1 activity is associated with increased atherosclerotic lesions in apoE−/− mice and in coronary artery disease (CAD) patients." (PMID 29879989, 2018). "Meta-analysis results of the associations between APOE ε2/ε3/ε4 polymorphisms and risk of coronary artery diseases in type 2 diabetes patients." (PMID 29311965, 2017). "And it was showed that the APOE variants result in a 2-fold or greater increased risk for coronary artery disease, myocardial infarction, and ventricular fibrillation." (PMID 29074556, 2017). "The APOE gene is located on chromosome 19 and encodes three alleles, ε2, ε3 and ε4, which have been shown to affect the lipid profile and the development of coronary artery disease (CAD)." (PMID 28727855, 2017). "Demographic, cognitive and APOE characteristics of the study subgroups divided according to their cardiovascular risk using the Framingham Coronary Heart Disease Risk profile index." (PMID 28184203, 2017). "In several studies, the relationship between ApoE gene polymorphism and severity of coronary artery disease (CAD) has been shown." (PMID 26380146, 2015). "Danhong Injection (DHI), a Chinese medicine for treatment of patients with coronary heart disease, inhibits primary abdominal aortic aneurysms in apoE deficient (apoE−/−) mice." (PMID 26061387, 2015). "The present study investigated the effect of ApoE gene polymorphism on severity of coronary artery disease in acute MI." (PMID 26380146, 2015). "The aim of this study was to evaluate the relationship between ApoE gene polymorphism and severity of coronary artery disease in patients with acute MI by using the Gensini scores in the southeast region of Turkey." (PMID 26380146, 2015). "An autopsy study suggested that the risk of developing and dying from cardiovascular disease, including coronary heart disease and cerebrovascular disease, was influenced by the APOE polymorphism." (PMID 24571688, 2014). "Prevalence of APOE ε4 alleles was significantly higher in patients with coronary artery disease than controls." (PMID 24621278, 2014). "•We examined evidence for an interaction between APOE genotype, smoking and risk of coronary heart disease." (PMID 25173947, 2014). "ApoE is considered as an excellent candidate gene for studying the susceptibility to coronary heart disease (CHD) and MI because of its pivotal roles in the metabolisms of cholesterol and triglyceride." (PMID 25111308, 2014). "Integrating instrumental or laboratory assessments like MRI data, APOE genotype, history of coronary artery disease, and diagnostic assessments such as cognitive tests, would almost certainly increase the predictive power of a risk index for AD." (PMID 24465922, 2014). "Numerous studies have evaluated the association between the apolipoprotein E (apoE) gene polymorphisms in coronary heart disease (CHD)." (PMID 24755673, 2014). "Although the prevalence of the APOE E4 allele is generally low, there are areas with higher prevalence of the APOE E4 allele and a higher incidence of adult ischemic heart disease mortality in Spain." (PMID 24571688, 2014). "The aim of this study was to study the association of the Apolipoprotein E genotypes with coronary artery disease in the Iranian population." (PMID 23997914, 2013). "The most common apolipoprotein E (apoE) gene polymorphism has been found to influence plasma lipid concentration and its correlation with coronary artery disease (CAD) has been extensively investigated in the last decade." (PMID 22520940, 2012). "The APOE ε4 allele is also strongly linked with increased risk of Parkinson disease, schizophrenia, and coronary artery disease." (PMID 19421411, 2009).
coronary artery disease (continued). "Although APOE ε4 allele carriage confers a risk for coronary artery disease, its persistence in humans might be explained by certain survival advantages (antagonistic pleiotropy)." (PMID 38509472, 2024). "Furthermore, a study that used tagged SNPs to investigate the association of variants in the APOE/C1/C4/C2 gene cluster with plasma lipid concentration reported a reduced risk of coronary heart disease in UK men harboring rs5127." (PMID 38003484, 2023). "Similarly, high expression of miR-16 in ApoE−/− mice fed a high-fat diet showed an anti-inflammatory effect of miR-16 on interleukine-6, and it was negatively associated with the severity of coronary artery disease." (PMID 34440258, 2021). "However, its locus has been extensively linked to coronary artery disease (neighboring genes are APOE, APOC1, and TOMM40)." (PMID 29527417, 2018). "Polymorphisms of APOA1 are associated with coronary artery disease and it is an interactor of the APOE, a well‐described genetic risk factor for Alzheimer's and cardiovascular diseases and the locus with the largest statistical support for an association with extreme longevity." (PMID 28295945, 2017). "On the other hand, one recently published review of Asian populations showed that the ε3 allele was likely related to coronary heart disease, indirectly demonstrating that APOE ε3/ε3 was a probable risk genotype for glycolipid metabolic disorder in Asian populations." (PMID 26998902, 2016). "Data on correlations of plasma apoE with levels of lipids and lipoproteins stratified by APOE genotypes as well as data exploring the association between plasma levels of apoE and risk of ischemic heart disease (IHD) are wanted." (PMID 26937471, 2016). "Also, our genetic data would be useful for the case-control association study of APOE genotype with other diseases such as type 2 diabetes and coronary artery disease in our population." (PMID 27078154, 2016). "APOE variants have been associated with blood lipid levels, familial dyslipoproteinemia, polygenic dyslipidemia, elevated plasma C-reactive protein levels, coronary heart disease, and myocardial infarction." (PMID 24922540, 2014). "Although meta-analyses suggest that APOE E4 carriers may have a 40–50% increased coronary artery disease risk, the associations reported in individual studies are highly heterogeneous." (PMID 24571688, 2014). "In addition, a –219 (G>T) polymorphism in the APOE promoter has in vitro been shown to decrease transcriptional activity of APOE and has been reported to associate with severity of coronary artery disease and increased risk for myocardial infarction." (PMID 17356695, 2007). "It remains uncertain whether this elevated risk is solely attributable to ε4-associated hypercholesterolemia and coronary artery disease, or whether additional brain-specific mechanisms are involved, such as the role of APOE in astrocytes and pericytes at the BBB." (PMID 40943807, 2025). "The ε4 allele (rs429358) allele has been described as a risk factor for coronary artery diseases (CAD) and is linked to low APOE concentrations, according to a different Italian investigation." (PMID 38540308, 2024). "Furthermore, genetic variations in genes that play a role in lipid metabolism, including cholesteryl ester transfer protein, lipoprotein lipase, low-density lipoprotein receptor, and apolipoprotein E, have the potential to influence the risk of coronary artery disease." (PMID 39203810, 2024). "Apo lipoprotein-E (APOE) encoded by APOE gene, is a plasma glycoprotein of 34.15 kDa and has a significant genetic association in coronary artery disease (CAD) progression." (PMID 35655909, 2021). "We now apply our framework to estimate the extent to which genetic variation at the APOE locus modulates the risk of coronary artery disease (CAD) due to statin treatment using UK Biobank data." (PMID 34495953, 2021).
coronary artery disease (continued). "In addition, 4G/5G polymorphism of the PAI-1 gene may modify the inhibitor’s synthesis, and it has been postulated that the mutation of apolipoprotein E gene (E2/E3) is associated with coronary artery disease." (PMID 31627731, 2019). "In addition, our analyses suggested that genetic variations at the ANKS1A, COL4A2 and APOE loci previously found associated with coronary artery disease in the general population could have stronger effects in patients with type 1 diabetes." (PMID 29695241, 2018). "We evaluated, for the first time in an Afro-Caribbean population, the distribution of APOE polymorphisms and their associations with coronary artery disease (CAD), the lipid profile and other cardio-metabolic risk factors." (PMID 28727855, 2017). "Epidemiological studies have evaluated the association between apolipoprotein E (ApoE) gene polymorphism and coronary artery disease (CAD) risk which developed inconsistent conclusions." (PMID 23826174, 2013). "A study from India, conducted on patients with coronary heart disease (CHD) and controls, concluded that the APOE E4 allele is more prevalent in the case cohort, at 15.1% in patients and 6.7% in controls." (PMID 40625502, 2025). "This study demonstrates that IF inhibits platelet activation and thrombosis in both patients with coronary artery disease and apolipoprotein E (ApoE) knockout (ApoE−/−) mice, by enhancing intestinal flora production of indole-3-propionic acid (IPA)." (PMID 40078933, 2025). "Genetic variations in SR-BI and apoE, which are lipoprotein receptors, significantly impact lipid levels, thereby contributing to the development of coronary artery disease and even MI." (PMID 38850523, 2024). "Due to its better affinity for LDL receptors than apoB-100, APOE can promote the clearance of VLDL and LDL from plasma, reducing ischemic heart disease risk." (PMID 36771367, 2023). "A study reported that methylation of APOE is significantly lower in men with coronary heart disease than healthy control men and is inversely proportional to APOE plasma levels." (PMID 35246549, 2022). "APOE is central to the transport and metabolism of lipids and plays an important role in both cerebral IS and coronary heart disease." (PMID 35754821, 2022). "The exposure of APOE e4e4 carriers to contemporary environmental conditions, such as a Western diet, sedentarism, and longer lifespans, could have led this allele to become a susceptibility allele for peripheral atherosclerosis, coronary artery disease, and several neurodegenerative diseases." (PMID 36357490, 2022). "The Tiaopi Huxin recipe, a traditional Chinese medicine widely used to treat coronary heart disease, was recently shown to decrease the expression of caveolin-1, thereby improving endothelial function and reducing atheromatous lesions in ApoE-/- mice." (PMID 32257548, 2020). "Some studies have shown an increase in apoD in the HDL proteome of individuals with coronary artery disease and in areas of human atherosclerotic lesions as well as in apoE knockout mouse plasma." (PMID 32921312, 2020). "In the Tunisian population the APOE E4 appears to be only indirectly involved in the severity of coronary artery disease." (PMID 24456740, 2014). "Objective(s): Apolipoprotein E genotype (APOE) polymorphism affects lipid levels and coronary artery disease (CAD) risk." (PMID 23997914, 2013). "Thoracic aorta samples were obtained from Apolipoprotein E knockout mice, and plasma samples were from coronary artery disease (CAD) patients." (PMID 23189122, 2012).
coronary artery disease (continued). "Some of these gene polymorphisms, such as insertion/deletion (I/D) polymorphism of the ACE gene, and apolipoprotein E (APOE) have been reported as a disease-candidate risk for ICA stenosis and coronary artery disease." (PMID 20066125, 2009). "Statistical interactions were detected, such that prolonged QT and JT intervals were significantly associated with reduced GM volume only among participants with coronary heart disease or without APOE ε4 allele (p < 0.05)." (PMID 38956440, 2024). "We are planning to establish gene re-knockout in ApoE (-/-) mice to verify whether double knockout mice can obtain more severe coronary heart disease models." (PMID 38715006, 2024). "Three apoE isoforms exist in humans—apoE2, apoE3, and apoE4—and it is in this order that these genotypes are associated with increasing LDL-cholesterol levels and coronary artery disease." (PMID 38388172, 2024). "The enrichment of apoE content in VLDL has been shown to protect against coronary heart disease." (PMID 36267630, 2022). "Patients in the low ApoE-HDL-C group had more significant coronary artery stenosis classified by Coronary Artery Disease Reporting and Data System (CAD-RADS) as 4A (severe stenosis, 11% vs. 2%) and 5 (total occlusion, 10% vs. 3%) as compared with the high ApoE-HDL-C group (overall P < 0.001)." (PMID 35389891, 2022). "This was necessary due to known associations between ApoE and non-AD traits, such as coronary artery disease, violating the MR exchangeability assumption." (PMID 33879569, 2021). "Plasma apoE levels are inversely associated with the risk of ischemic heart disease in men, but not in women, and this relation is likely dependent on TG levels rather than the affinity (that is genetically determined) of apoE for its receptor." (PMID 34440638, 2021). "Indeed, ivabradine improved endothelial function in ApoE knockout mice by reducing vascular oxidative stress and preventing endothelial NO synthase uncoupling and in patients with coronary artery disease after complete revascularisation." (PMID 32754607, 2020). "Previous work has shown that probucol, an antioxidant biomolecule, also exhibits an anti-atherogenic effect in double SR-B1/apoE KO mice, another model of lethal coronary heart disease very similar to atherogenic diet-fed SR-B1 KO/ApoER61h/h mice used in this investigation." (PMID 30219096, 2018). "Examples include the association of the APOE/TOMM40 locus with pancreatic cancer and total cholesterol levels, the association of the ABO locus with macular degeneration and coronary artery disease, and the association of the SH2B3/ATXN2 locus with diastolic blood pressure and rheumatoid arthritis." (PMID 26677855, 2015). "ApoD may be directly involved in regulation of SR-BI levels as SR-BI−/−: apoE−/− double knockout mice, a mouse model of coronary heart disease (CHD), had significantly higher apoD mRNA expression levels." (PMID 25548917, 2014). "Thus, SR-BI/apoE dKO mice provide a very rapid, small animal model that mimics many cardinal features of human coronary heart disease." (PMID 19956623, 2009).